CXCR4 (C-X-C motif chemokine receptor 4)
Diseases named in the same sentence as CXCR4 in open-access papers (continued):
Sharing a sentence is not in itself a finding about the gene and the disease.
tumor (continued). "CXCR4-positive OSCC tumors metastasized to lymph nodes and to distant organs more frequently than CXCR4-negative tumor cases." (PMID 31336612, 2019). "Several studies have found that attraction of tumor cells to the bone marrow is dependent on the dual interactions of SDF-1α and its receptor CXCR4 in both cancer cells and MSCs." (PMID 31130595, 2019). "A high dose of CLG inhibited the growth of transplanted tumor and liver metastasis of CRC in nude mice, probably by inhibiting the HIF-1α/SDF-1α-CXCR4/PI3K-Akt signaling pathway reducing the synthesis and release of VEGF and degradation of collagen IV." (PMID 30789971, 2019). "Collectively, AGTR1 promotes LNM by increasing the chemokine pair CXCR4/SDF-1α and tumor cell migration and invasion." (PMID 31219799, 2019). "Similar relationships with tumor grading have been found previously for SST2A expression, CXCR4 expression, and Ki-67 values." (PMID 30867449, 2019). "Many bioactive compounds from traditional Chinese medicines show anti-tumor effects on TNBC, and some of these compounds inhibit CXCR4 expression in TNBC cells." (PMID 32047724, 2019). "Considering its pleiotropic effects in tumour development, the CXCL12/CXCR4 axis is considered as a potential target for cancer treatment." (PMID 31752959, 2019). "As the CXCR4 receptor for CXCL12 is expressed on both the tumor cells and EPCs, CAF-produced CXCL12 stimulates tumor growth and neoangiogenesis via acting CXCR4 expressed on these cells." (PMID 31067787, 2019). "As a member of chemokine subfamily, SDF-1 binding with its receptor CXCR4 triggers CRC cells migration, promoting tumor metastasis." (PMID 30789971, 2019). "As a result, increased ratio of pro-apoptotic to anti-apoptotic gene expression undermines the immortality of tumor cells, while the reduced level of CCR7 and CXCR4 compromises their migratory capability." (PMID 31507423, 2019). "Numerous studies are trying to shed light upon the tumor roles of CXCL12, such as its effects at cellular levels and interactions with CXCR4 and ACKR3 receptors." (PMID 31275385, 2019). "Similar to what we observed in tumours, RTCT increased rectal CXCR4 expression and the accumulation of immune cells, including T-cells (CD4, CD8), MDSCs (Ly6G) and macrophages (F4/80)." (PMID 31239542, 2019). "The CXCL12 (SDF-1)/CXCR4/CXCR7 axis, which has been shown to contribute to tumor progression by modulating cancer cell survival, proliferation and migration, also seemed to be involved in the ASC/H295R cell crosstalk." (PMID 31817072, 2019). "The subcellular distributions of CXCR4 and HIF-1α in the primary tumor tissues served as predictors of metastasis in RCC, while they were not related to the presence of metastases." (PMID 30177838, 2019). "This brings out the key role played by CXCR4 in enabling the recruitment of eIF4G and LASP1 to enable the synthesis of oncogenic proteins involved in tumor progression and metastasis." (PMID 31106142, 2019). "We compared the CXCR4 and PTGS2 expression in the tumors with the expression in the starting cell lines and observed a dramatic increase in tumor tissue for all samples except the MDMX knockdown cells." (PMID 30642351, 2019). "To confirm that CXCR4:CXCL12 axis contributes to the seeding of the bone chip at the metastatic site, we repeated the tumor xenograft at the primary site and the human bone at the metastatic site experiment with the addition of AMD3100, a CXCR4 inhibitor." (PMID 31628348, 2019). "Our results showed that the cells with ectopic FAM289 expression significantly enhanced the tumor-sphere forming ability and increased the proportion of stemness factor CD133, Ki67 and chemokine CXCR4 expression." (PMID 31492191, 2019). "CXCL12 and CCL2 can promote angiogenesis and inhibit apoptosis of endothelial cells by directly binding their receptor (CXCR4 and CCR2, respectively) expressed on tumor vessels or indirectly promoting the recruitment of leukocytes." (PMID 30894861, 2019).
tumor (continued). "M2 TAMs can produce growth factors and cytokines such as CCL2, CXCL12, CXCR4, TGFβ, VEGF, PDGF, COX-2 and metalloproteinases that determine immunesuppression and stimulate local tumor growth as well as the metastatic process." (PMID 31500586, 2019). "In tumor microenvironment, CXCR4+ MDSCs and neutrophils can be recruited by CXCL12 and they impair the anti-tumor functions of CD8+ cytotoxic T cells leading to increased tumor metastasis." (PMID 30808413, 2019). "The specific recognition ability and anti-cancer effect of the CXCR4-targeted NPs were evaluated in the CXCR4-expressing HCC cells and tumor xenograft models." (PMID 31151472, 2019). "Therefore, while the expression of human CXCR4 in host tumour-infiltrating cells may contribute to increase ADC 713 TMDD, it is possible that the global anti-tumour activity (i.e., towards both cancer cells and their supporting stroma) of ADC 713 in solid tumours was underestimated in our studies." (PMID 30792442, 2019). "In intrahepatic cholangiocarcinoma, activated hematopoietic stem cells (HSCs) promote tumor fibrogenesis, tumor progression and distant metastasis by mediating the epithelial-mesenchymal transition (EMT) via the Ang II/AGTR1 and CXCR4/SDF-1α axes." (PMID 31219799, 2019). "We validated the downregulation of PTGS2 and CXCR4 with MDM2 and MDMX knockdown in the tumors by performing qRT-PCR from the sets of primary tumor samples." (PMID 30642351, 2019). "It has been shown that CAFs as well as tumor cells secrete SDF-1/CXCL12, which is the ligand for CXCR4." (PMID 31663852, 2019). "The present findings also suggest that the C-terminal modification of LY2510924 may also provide CXCR4-targeting probes for other imaging modalities (e.g., magnetic resonance imaging, fluorescence imaging) and CXCR4-targeting therapeutics with cytotoxic drugs for tumor treatment." (PMID 31653903, 2019). "It has been proved that SDF-1/CXCR4 is highly expressed in CRC tissue, and the intensity of expression is closely related to tumor stage and lymph node and distant metastasis." (PMID 30789971, 2019). "We observe the downregulation of several activation receptors including CD16, CD62L, C-X-C chemokine receptor (CXCR)-4, natural killer group 2 member D (NKG2D), DNAX accessory molecule (DNAM)-1, and NKp46 following tumor-priming." (PMID 31242243, 2019). "The chemokine SDF-1 (CXCL12), which binds to G protein-coupled receptors CXCR4 and CXCR7, plays an important role in tumor growth and metastasis in different tumor types." (PMID 30874597, 2019). "On the other hand, inhibition of CXCR4 reduces VEGF secretion in tumor cells, which results in decreased neovascularization and tumor growth." (PMID 30800123, 2019). "This is consistent with the very high level of CXCR4 expression in poor prognosis CRC and other neoplasias in comparison with non‐tumor tissues." (PMID 30190334, 2018). "EGFR over-expression and 19 exon deletion can promote the expression of MMP-2 and MMP-9 by up-regulating CXCR4/CXCL12 signaling pathway, leading to the change of tumor biological characteristics such as higher proliferation, migration and invasion ability." (PMID 30037369, 2018). "It was reported that activation of CXCR4 and CCR5 leads to the activation of AKT and promotes tumor proliferation." (PMID 30200472, 2018). "The molecular basis underlying our findings on DLBCL, as in those in other tumor types, in which CXCR7 is a marker for good prognosis may relate to a protective effect reported for CXCR7 expression, which has been always associated with the inhibition of CXCR4-mediated signaling." (PMID 29920526, 2018). "In cancer, CXCR4 expression and its activation by its endogeneous ligand CXCL12 are key triggers for tumor growth and progression, invasiveness, and metastasis." (PMID 30191351, 2018).
tumor (continued). "Chemokine axes, such as fractalkine (CX3CL1)/CX3CR1, C-X-C motif chemokine ligand 12 (CXCL12)/C-X-C chemokine receptor type 4 and 7(CXCR4/CXCR7), CCL2/CCR2, and CCL5/CCR5, are clearly involved in tumor progression." (PMID 30123112, 2018). "MiR‐9 knockdown, similar to CXCR4 overexpression, significantly promoted aggressive HNSCC tumour cell characteristics." (PMID 29959873, 2018). "CXCL12-induced migration is enhanced in CXCR4+/CXCR3+/CD8+ T lymphocytes and in CXCR4+/CXCR3− malignant B cells, indicating that chemotactic cues in the perivascular environment serve as regulators for the recruitment of tumor infiltrating lymphocytes (TILs)." (PMID 30319638, 2018). "It is noteworthy that resveratrol strongly suppressed TNF-β-induced activation of tumor-promoting factors (NF-κB, MMP-9, CXCR4) and epithelial-to-mesenchymal-transition-factors (increased vimentin and slug, decreased E-cadherin) in CRC cells." (PMID 30002278, 2018). "CXCR4, the receptor for the chemokine stromal-derived factor 1 (SDF-1), mediates essential processes for tumor progression, such as metastasis." (PMID 29867502, 2018). "In addition, the interaction of Paget cells with other cells, such as LECs and CD163+Arg1+ macrophages in a tumor through the CXCR4–SDF-1 signaling and RANKL–RANK signaling, respectively, could establish a favorable tumor microenvironment to promote metastasis of Paget cells." (PMID 29503810, 2018). "In contrast, in both the M5 and SW1417 models we observed only a low and non‐significant reduction in CXCR4+ CCF in the organs showing low sensitivity to T22‐GFP‐H6‐FdU, such as the primary tumor or LN Mets." (PMID 30190334, 2018). "In our data, we identified a switch from MMP1, 3 and 13 in primary tumours to MMP1, 9 and 12 in metastases, as well as a significant upregulation of CXCL12/CXCR4." (PMID 29743718, 2018). "It is also reported that malignant tumor cells express chemokine receptors such as CCR7, CXCR1, and CXCR4 that can increase their invasiveness as well as survival." (PMID 30483271, 2018). "The TMA with combined primary tumour and metastasis tissue was tested for Connexin, Tks5, MAD, TWIST, vimentin, PLCγ, and CXCR4." (PMID 29976164, 2018). "In a mouse model of PDAC, fibroblast activating protein-expressing CAFs produce CXCL12 that coats tumor cells and prevents CXCR4+ CD8+ T cells from infiltrating tumor nests and controlling the tumor." (PMID 30498499, 2018). "Th17 cells, mostly mediating potent antitumor immunity by recruiting CD8+ T cells, NK cells, and dendritic cells (DCs) into the tumor microenvironment, express high levels of CCR6 and CXCR4 and low levels of CCR7." (PMID 30591657, 2018). "HIF acts on HREs to promote the expression of CXCR4 on the surface of Tregs cells, which in turn bind to CXCL12 on the surface of tumor cells, and then Tregs are recruited by chemotaxis into tumor tissues." (PMID 30477520, 2018). "This study demonstrates a clear tumour suppressor role for miR‐9 in HNSCC and suggests that the potential oncogenic effects of miR‐9 knockdown in HNSCC are mediated through targeting CXCR4." (PMID 29959873, 2018). "When the Chemokine C-X-C Motif Receptor Type 4 (CXCR4), whose expression can be enhanced by hypoxia, binds Stromal Cell-derived Factor 1 (CXCL12), secreted by CAFs, release of MMP-9 to the tumour microenvironment is stimulated." (PMID 29743718, 2018). "Overall, the level of CXCR4 and CXCL12 expression is predictive for the metastatic potential of a given tumor type and mediates organ-specific metastasis." (PMID 30105558, 2018). "To confirm the relevance of TAMs in favoring the aggressiveness of BC cells, we performed double immunofluorescence for CXCR4 and CD163 on tumor tissues of luminal B BC patients from the validation cohort." (PMID 29849822, 2018). "Our data demonstrate a clear role for miR‐9 as a tumour suppressor microRNA in HNSCC, and its role seems to be mediated through CXCR4 suppression." (PMID 29959873, 2018).
tumor (continued). "The combination of chemokine CXCL12 and its receptor CXCR4 can up-regulate the expressions of MMP-2 and MMP-9 in tumor cells and reduce the secretion of tissue inhibitor of metalloproteinases (TIMPs)." (PMID 29305742, 2018). "CXCL12 binds to CXCR4 and CXCR7 chemokine receptors, which have important roles in tumor proliferation, metastasis, and angiogenesis, as well as regulation of leukemia stem cell migration." (PMID 29301363, 2018). "Most stem cell markers were expressed at only a low level in the both core and periphery of the tumor, except for Sox2 and CD44, which showed high expression in both sites, and CXCR4, which showed slightly higher expression in the periphery." (PMID 30210550, 2018). "It has been shown both in tumor models and in our previous work in a cell culture model that the CXCL12/CXCR4 axis promotes the expression of VEGF both at the mRNA and protein levels, most likely through the Akt pathway." (PMID 29751775, 2018). "Stimulation of PI3K by CXCR4 triggered signaling is led by the activation of AKT (a.k.a, protein kinase B) and its downstream targets, some of which induce migratory activity in tumor cells." (PMID 29973594, 2018). "There is evidence that disruption of CXCR4 results in a reduction of GBM stem cell markers and reduction in tumor cell proliferation." (PMID 30413179, 2018). "Many tumor cells have the ability to produce CXCL12, whose extracellular bioavailability can be modulated by the cell-surface expressed CXCR4 and CXCR7." (PMID 29977203, 2018). "Furthermore, we have seen that ACKR3 can induce ERK and Akt phosphorylation in a different kinetic and spatial sequence to CXCR4 and alter receptor internalization and thus may still be involved in other pathways such as NF-κB-mediated survival, tumour growth and angiogenesis." (PMID 30441765, 2018). "Pericytes are recruited into tumor blood vessels in PDGF-B/PDGFRb, HB-EGF/Erb and SDF-1a/CXCR4 dependent manner." (PMID 29519245, 2018). "Studies have also shown that the combination of CXCL12 and its receptor CXCR4 can activate NF-κB and increase the secretion of MMP-2 in tumor cells." (PMID 29305742, 2018). "The results delineate increased expression of angiogenic and oncogenic markers CXCR4, SDF-1, and decreased expression of tumor suppressor genes, IRF1, LDOC1, and FOXO3 in CP patient tissues." (PMID 30413788, 2018). "We have shown increased expression of metastasis markers CXCR4, SDF-173,74 and decreased tumor suppressor molecules LDOC1 and FOXO3, induction of oncogenes and promotion of tumor growth." (PMID 30413788, 2018). "Hypoxia significantly impacts on the TAM tumour cell interaction that induces the expression of CXCR4 and its ligand, CXCL12 (SDF-1), further supporting tumour cell dissemination and angiogenesis." (PMID 29507865, 2018). "Comparing relative receptor expression intensities between the two tumor entities, CCCs showed significantly higher intensities of expression of SSTR1, SSTR2, SSTR5, and CXCR4 than HCCs." (PMID 29282035, 2017). "Excitedly, our results showed QRHX treatment inhibited signaling from tumor cells to macrophages through inducing a remarkable decrease in CXCL12 and CXCR4." (PMID 28630636, 2017). "Most notably and in contrast to the scarce staining of tumor cells, exceptionally strong staining of tumor capillaries was noticed for both ETA (89.5% of cases) and CXCR4 (73.7% of cases)." (PMID 29163802, 2017). "Expression of tumor-induced factors responsible for MDSCs’ differentiation and proliferation, such as, TGFβ, MMP9, IL-6, VEGF, CXCR4, CCL2 was upregulated in MDSCs from CD8 depleted NLGP immunized mice, that was in downregulation after NLGP treatment." (PMID 28414726, 2017). "In this study, we addressed this question by measuring the expression of CXCR4, CXCL12, and Cyclin D1 proteins in tumor samples from Chinese patients with sporadic MPNST." (PMID 29020982, 2017).
tumor (continued). "CXCR4 is a chemokine receptor of the ligand stromal cell-derived factor 1 (SDF1), which is reported to be a mediator of tumor invasion and metastasis." (PMID 28245823, 2017). "To overcome this issue, we can combine the cancer targeted-OAd with tumor specific promoters, such as COX-2 or CXCR4 promoters." (PMID 29100290, 2017). "The macroscopic tumor size was significantly smaller in the MNU-treated Tie2-Cre; Cxcr4-EGFP; Cxcl12flox/flox mice compared to controls." (PMID 29340033, 2017). "Upon coinjection with 50 μg AMD3100, tumor accumulation is reduced to background levels, demonstrating that tumor uptake of [64Cu]NOTA-pentixather is almost exclusively CXCR4-mediated." (PMID 29527563, 2017). "Among these, the system formed by the chemokine receptor CXCR4 and its cognate ligand, the chemokine SDF-1α/CXCL12, has been highlighted to play a crucial role in multiple mechanisms sustaining tumor progression." (PMID 28423060, 2017). "The inhibition of CXCR4 restrained stem cells-like properties (metastasis and chemoresistance) of CD133+/CXCR4+ stem cells derived from human NSCLC tumor tissues." (PMID 28076327, 2017). "Independent from the tumor cells, many samples displayed strong staining for SSTR5 and CXCR4 on capillaries of the tumor stroma." (PMID 29282035, 2017). "By contrast, ACKR3 became markedly upregulated as up to 50% of the conditioned cells (ex vivo) expressed the receptor, indicating that after localized tumor passage the presence of two populations existed, namely ACKR3+/CXCR4+ and ACKR3-/CXCR4+cells." (PMID 29156704, 2017). "By binding to the C–X–C chemokine receptor type 4 (CXCR4), C–X–C ligand (CXCL) 12 is known to be involved in tumor development and metastasis." (PMID 29383153, 2017). "While other studies focused only on the role of chemokines or mifepristone in tumor development, we revealed the function of mifepristone on tumor progression and metastasis via interfering with the SDF-1/CXCR4 axis." (PMID 28938623, 2017). "Other anti-CXCR4 antibodies, including ulocuplumab, LY2624587, and hz515H7, were also shown to induce tumor cell death upon binding to CXCR4; however, the role of antibody bivalency in this process was not described in these studies." (PMID 28526063, 2017). "Silencing CXCR4 or COX2 remarkably reversed the induced cell migration in surviving cells, identifying the definitive role of IR-induced CXCR4 and/or COX2 in tumor cell migration." (PMID 27974694, 2017). "CXCR4/AlexaFluor488 and PepR-NIR750 staining overlapped in B16-CXCR4 tumor sections confirming the same target for PepR-NIR750 and CXCR4/AlexaFluor488." (PMID 28566721, 2017). "In summary, we report that miR-199a-5p plays a tumor-suppressive role by directly targeting HIF-1α and thereby suppresses genes downstream of HIF-1α, such as VEGF, CXCR4, BNIP3 and BCL-xL." (PMID 29137361, 2017). "Blockade of both CXCR4 and PD-1 prevents suppression of immune cell function in HCC tumors, enhances immune cell tumor penetration and activation, and ultimately delays HCC progression." (PMID 29100374, 2017). "The monoclonal antibodies against SSTR1, SSTR2, SSTR3, SSTR5, and CXCR4 produced distinct immunostaining of the plasma membrane, but also of the cytoplasm of the HCC and CCC tumor cells." (PMID 29282035, 2017). "Previously, cellular subpopulations from tumor tissue such as CD54+CD44+18, CD26+27, CD133+CD44+28, and CD133+CXCR4+29 had been sorted and identified as CICs or MICs." (PMID 29105339, 2017). "Biomarker expression of CXCR4, SMAD4, SOX9 and IFIT3 will be prospectively assessed by immunohistochemistry and verified by rt.-PCR from tumor and adjacent healthy pancreatic tissue of surgical specimen." (PMID 28356064, 2017). "The influence of PT on tumor cell adhesion and transmigration onto/through the endothelium as well as its influence on cell adhesion molecules and the chemokine system CXCL12/CXCR4 was investigated." (PMID 29100413, 2017).